SNORA68 (small nucleolar RNA, H/ACA box 68)
Synonyms: U68; SNORA68A; RNU68
Gene: Small nucleolar RNA gene on chromosome 19 (17,862,588 to 17,862,720, forward strand). Ensembl gene ENSG00000207166.
Gene Ontology:
Biological process: RNA processing
Cellular component: nucleolus
Homologues: Orthologues: chimpanzee SNORA68 (98% identical), dog SNORA68 (86% identical), guinea pig SNORA68 (81% identical), pig SNORA68 (79% identical), rat LOC120097581 (76% identical), mouse Snora68 (73% identical). Paralogues in human: SNORA68B (89% identical).
Diseases named in the same sentence as SNORA68 in open-access papers:
SNORA68 is named in the same sentence as 4 diseases in open-access papers, as found by Europe PMC text mining. Sharing a sentence is not in itself a finding about the gene and the disease. The quoted sentences say what the papers report.
glioblastoma (1 paper, 2015). The most malignant astrocytic tumor (WHO grade IV). "Among the ten most upregulated genes, five (SNORA20, SNORA71A, SNORA23, SNORA3, SNORA68) were recently found to be downregulated by HOXA10 in LN18 glioblastoma cells." (PMID 26362268, 2015).
schizophrenia (1 paper, 2019). A major psychotic disorder characterized by abnormalities in the perception or expression of reality. "Although non-coding RNAs such as small nucleolar RNAs (snoRNAs), microRNAs and long non-coding RNAs (LncRNAs), have been studied in disease etiology, the involvement of SNORA38B, SNORA68, SNORA23, SNORA20, and SNORA3A in the pathogenesis of schizophrenia has yet to be reported." (PMID 30967896, 2019).
tumor (3 papers, 2019 to 2025). "Taken together, our results demonstrate that SNORA68 participates in maintaining the stem cell properties of TNBC cells to attenuate tumor initiation." (PMID 38594783, 2024). "SNORD15B, SCARNA3, and RNU2-1 snRNA also appear to have tumor-suppressive potential, whereas the evidence for oncogenic roles of SNHG1 and SNORA68 was less convincing." (PMID 41283331, 2025).
SNORA68 also shares sentences with these, for which no sentence is quoted: asthma (1 paper).